TLR4 (toll like receptor 4)
Diseases named in the same sentence as TLR4 in open-access papers (continued):
Sharing a sentence is not in itself a finding about the gene and the disease.
necrotizing enterocolitis (continued). "In an experimental necrotizing enterocolitis model, this L. reuteri strain significantly reduces intestinal inflammation, inhibiting TLR4 and NF-KB receptor expression, in addition to modulating effector and regulatory T cells." (PMID 30669695, 2019). "Necrotizing enterocolitis (NEC) that affects the immature intestine shows its devastating consequences partially due to the high expression of TLR4, which results in the induction of inflammatory cytokines and impairment of the epithelial barrier." (PMID 31847111, 2019). "Lipopolysaccarides (LPS) is an outer membrane virulence factor of E. sakazakii, which interacts with enterocytes through LPS mediated binding to toll like receptor-4 (TLR4) inducing necrotizing enterocolitis in animals." (PMID 29234307, 2017). "It has been shown that feeding L. reuteri DSM 17938 to newborn rats in an animal model of necrotizing enterocolitis (NEC) induced a strong anti-inflammatory effect through inhibiting TLR4 signaling pathway in the intestine." (PMID 27014275, 2016). "Intestinal Hsp72 overexpression reversed toll-like receptor (TLR)-4-induced cytokines and enterocyte apoptosis and prevented and treated experimental necrotizing enterocolitis." (PMID 24524071, 2014). "We have recently shown that LR17938 reduces the incidence and severity of experimental necrotizing enterocolitis via modulation of TLR4 and NF-κB signaling in the intestine." (PMID 23437165, 2013). "High levels of TLR4 in necrotizing enterocolitis (NEC) activate necroptosis of intestinal epithelial cells, contributing to local inflammation that may have been prevented by the use of Necrostatin-1, a necroptosis inhibitor." (PMID 35501340, 2022). "Inhibiting HMGB1 could improve intestinal inflammation in necrotizing enterocolitis by inhibiting NLRP3 via the TLR4 signalling pathway." (PMID 35197507, 2022). "Interestingly, 2′-FL and 6′-SL were found to directly bind to TLR4 and inhibit TLR4 signaling in ex vivo gut tissue and organoid cultures, explaining the protection against the necrotizing enterocolitis in newborn mice and premature piglets." (PMID 33829032, 2021). "For instance, TLR4 hyperactivation in premature mice and humans has been shown to lead to increased enterocyte apoptosis, reduced enterocyte proliferation and migration, and the eventual breakdown of the intestinal epithelium that is a hallmark of necrotizing enterocolitis (NEC)." (PMID 32499778, 2020). "Contrary to the beneficial effects of the pharmacological inhibitors on TLR4-induced inflammation, there is some evidence, related to the pediatric condition necrotizing enterocolitis, that TLR4 signaling may be essential for controlling inflammation." (PMID 29515999, 2018). "Similarly, Nod2 stimulation reduces LPS-triggered TLR4 activation and is protective in a model of LPS-induced necrotizing enterocolitis." (PMID 25423082, 2014). "The net effect of these TLR4-mediated responses leads to gut barrier failure, bacterial translocation, the development of systemic sepsis, and the clinical and pathologic features of necrotizing enterocolitis." (PMID 23762089, 2013). "It has also been shown that Bifidobacterium, including B. breve M16-V, has the ability to reduce the incidence of necrotizing enterocolitis (NEC) in part by down-regulating TLR4 signaling." (PMID 39006103, 2024). "On the other hand, the supplementation of AA and docosahexaenoic acid (DHA) inhibited intestinal TLR-4 gene expression and ameliorated NEC (necrotizing enterocolitis)." (PMID 37759732, 2023). "Necrotizing enterocolitis (NEC) brain injury is mediated through Toll-like receptor 4 (TLR4) on the intestinal epithelium and brain microglia." (PMID 37217588, 2023). "Dramatic intestinal epithelial cell death leading to barrier dysfunction is one of the mechanism of neonatal necrotizing enterocolitis (NEC), in which Toll-like receptor 4 (TLR4) plays a pivotal role." (PMID 33731807, 2022).
necrotizing enterocolitis (continued). "While surfactant protein A (SP-A) is known to regulate TLR4 in the lung, it also reduces intestinal damage, TLR4 and inflammation in an experimental model of necrotizing enterocolitis (NEC) in neonatal rats." (PMID 33510368, 2021). "Necroptosis is activated in a TLR4‐dependent manner in the intestine of mice with necrotizing enterocolitis (NEC) and specifically upregulated in differentiated epithelial cells of immature ileal." (PMID 34977874, 2021). "Neonatal mouse models of necrotizing enterocolitis exhibited reduced levels of HMGB1, TLR4, and inflammatory cytokines after butyrate pretreatment." (PMID 38709282, 2024). "In conclusion, this is the first study to show differences in DNA methylation of TLR4, VEGFA, and DEFA5 in infants affected by necrotizing enterocolitis." (PMID 33748044, 2021). "Exosomes can inhibit the activation of toll-like receptor 4 (TLR4) which was involved in intestinal inflammation and progression of necrotizing enterocolitis (NEC)." (PMID 34778341, 2021). "Furthermore, in a murine model of necrotizing enterocolitis (NEC), RA was able to reduce the severity of NEC by downregulating TLR-4-induction of IL-17 and to improve Tregs numbers and repopulation of LGR5+ intestinal stem cells." (PMID 30134532, 2018). "Our earlier studies have shown that in rodent models of necrotizing enterocolitis where PAF plays an important role, TLR4 expression is aberrantly elevated in the intestinal epithelium, implicating PAF in the regulation of TLR4 expression." (PMID 20976181, 2010). "Kovler and colleagues reported that mice lacking TLR4 on enteric glia retain their enteric glia but are protected from experimental necrotizing enterocolitis and do not develop dysmotility when experimental necrotizing enterocolitis is induced." (PMID 39606241, 2024). "The molecular determinants underlying this are complex with migration occurring more rapidly in mice lacking TLR4 in necrotizing enterocolitis but more slowly in septic mice lacking TLR4." (PMID 30923621, 2019). "This pattern of expression for TLR4 and TLR9 is inversed in tissue from infants suffering from necrotizing enterocolitis (NEC) and might be of pathophysiological relevance." (PMID 34054875, 2021).
steatosis (70 papers, 2012 to 2026). Increased lipid within the cytoplasm of cells. "In fact, TLR4- or TLR9-deficient mice given HFD or choline-deficient diet were protected from hepatic steatosis and inflammation." (PMID 36875849, 2023). "Deficiency of Tlr4 has been shown to prevent liver damage against both steatosis and steatohepatitis." (PMID 35343085, 2022). "The higher dose of CGA efficiently prevented the progression of alcohol-induced steatosis and reduced inflammation through regulation of the expression of genes encoding the proteins involved in the Tlr4/Nf-κB signaling pathway and fibrosis." (PMID 34836410, 2021). "While, TLR4 deficiency protected against alcohol-induced steatosis by protecting against inflammatory cytokines production." (PMID 34603062, 2021). "In FFC+SoB-fed mice, disease was limited to steatosis associated with protection against the induction of Tlr4 mRNA and iNOS protein levels in livers." (PMID 32235497, 2020). "For instance, WT mice fed on a high-fat diet, fructose-rich diet, methionine/choline-deficient diet or choline-deficient amino acid-defined diet have shown steatosis/steatohepatitis with increased TLR4 expression and proinflammatory cytokines in the liver." (PMID 31788011, 2019). "Our findings are in line with the studies of others in rodents and humans showing that the short-term intake of a high fat diet is associated with the development of steatosis and in rodents an activation of TLR-4-dependent signaling cascades in the liver." (PMID 28906444, 2017). "Indeed, TLR4- or TLR9-deficient mice treated with HFD or a choline-deficient diet were protected from steatosis-related liver failure and inflammation." (PMID 39997751, 2025). "Furthermore, TLR4 deficiency has been shown to reduce hepatic fat content, indicating its critical role in promoting steatosis." (PMID 39335657, 2024). "This protective effect might be associated with inhibiting steatosis, activating Nrf2/HO-1-mediated antioxidant defense, and suppressing TLR4/NF-κB -mediated inflammation." (PMID 33149748, 2020). "Our study aims to investigate these issues by exploring the connections between IL-17A/F, TLR4, and inflammatory markers, as well as their associations with the severity of steatosis and the likelihood of fibrosis, to identify new biomarkers that could guide future therapeutic strategies." (PMID 39335657, 2024). "However, the alteration in intestinal permeability, associated with the increase in circulating levels of LPS, TLR4 downstream signaling and TGFβ, may have an important role in the increased microvesicular steatosis and fibrosis." (PMID 36430244, 2022). "Subsequent hepatic Toll-like receptor 4 (TLR4) activation by translocated LPS stimulates immune cells, induces pro-inflammatory cytokine production, and drives progression from steatosis to fibrosis, accelerating NAFLD pathogenesis." (PMID 41514305, 2026). "This microbiota remodeling prevents LPS translocation to the liver and inhibits TLR4/NF-κB pathway activation, resulting in attenuated hepatic inflammation and steatosis." (PMID 40556760, 2025). "Blocking the TLR4/NF-κB cascade reversed the promoting effect of IREB2 on steatosis and inflammatory response." (PMID 39910919, 2025). "In HCC patients, pir-hsa-216911 was highly expressed in HCC tumor samples with steatosis, suppressing TLR4 expression and inhibiting GSDMD activation." (PMID 39824843, 2025). "Upregulation of serum and hepatic LPS, p-NF-κB and Toll-like receptor 4 (TLR4+) macrophages in patients with MASH were also increased compared to patients with simple steatosis and healthy controls." (PMID 39770690, 2024). "Arctic berry extracts (ABEs) were found to ameliorate steatosis in mice by alleviating hepatic inflammation, as evidenced by decreased mRNA expression of Tlr4." (PMID 39451562, 2024).
steatosis (continued). "This study proved that OLE, a component of EVOO, reduces liver inflammation and steatosis by lowering hepatic LPS localization and downregulating intestinal and liver TLR4+ macrophage in HFD-treated mice." (PMID 38891768, 2024). "Local and circulating eNAMPT directly activates the TLR4/NFκB-dependent inflammatory cascade to contribute to hepatic transition from steatosis to NASH and fibrosis." (PMID 36809677, 2023). "Seminal studies with knock out mice of MCP1/IRF3/TLR4/caspase-I have revealed that these mice are protected from various stages of ALD including steatosis, steatohepatitis, and fibrosis as inflammasome dependent signaling in KCs is inhibited." (PMID 38146363, 2023). "The inhibition of hypothalamic TLR4 by i.c.v. injection of anti-TLR4 antibody improves liver insulin signal transduction and reduces steatosis and gluconeogenesis." (PMID 37028769, 2023). "LPS/TLR4 signaling induces anti-viral responses, inflammation, steatosis, fibrosis, and hepatocarcinoma, as well as hepatic fibrosis-mediated portal hypertension, which leads to bacterial overgrowth and intestinal permeability." (PMID 36544761, 2022). "In high-fat diet-induced obese mice, liver TLR4 expression was significantly stimulated, while liver-specific knockout TLR4 rescued high-fat diet-induced liver injury and steatosis." (PMID 35355867, 2022). "In summary, our study provides strong evidence for the first time that Cim intervention prevents lipotoxicity-induced cell death and steatosis in hepatocytes via inhibiting TLR4/p38 overactivation and SIRT1 reduction." (PMID 35355867, 2022). "At the same time, activating TLR4 by its agonist (LPS) markedly abolished the beneficial role of Cim on lipotoxicity-induced hepatic cell death and steatosis." (PMID 35355867, 2022). "A higher number of TLR4-positive macrophages were observed in NASH patients in comparison to patients with simple steatosis and controls, where TLR4 expression was positively correlated with serum LPS levels." (PMID 36300120, 2022). "Some authors have described that the inhibition of the TLR4/NF-κB signaling pathway, which is related to inflammatory response in chronic liver damage, also helps to protect hepatocytes against steatosis and fibrosis." (PMID 34836410, 2021). "The livers of POA-treated mice exhibited less steatosis and inflammation than those of OA-treated mice with lower inflammatory cytokine levels and reduced toll-like receptor 4 protein content." (PMID 32738301, 2020). "To examine the effect of Tlr4 inhibition on hepatic NPC1L1‐mediated steatosis, we fed L1‐Tg mice a HFD containing IAXO101 (12 μg/g of feed), a commercially available synthetic antagonist of TLR4 signaling, for 2 weeks." (PMID 32123832, 2019). "Regarding the potential efficacy of TLR4 inhibition on NAFLD, we showed that oral administration of a TLR4 antagonist prevented steatosis in L1‐Tg mice." (PMID 32123832, 2019). "TLR4 mutant C3H/Hej mice and TLR4 knock-out mice had mitigated hepatic steatosis, inflammation and necrosis in ALD compared to wild type mice." (PMID 23087650, 2012). "There is increasing experimental evidence that choline and betaine reduce inflammation and steatosis in the liver, which may be correlated with their regulation of the TLR4 pathway." (PMID 38887554, 2024). "This study suggested that biotransformed PAC may be potent in reducing the progression of steatosis to NASH by mitigating cellular inflammation by suppressing TLR4/NF-κB and TLR4/MAPK inflammatory signaling." (PMID 38338453, 2024). "Parallel changes were detected in the liver of HFD mice that, in fact, displayed inflammatory fingerprints such as LPS accumulation in the liver cells, TLR4 macrophage over-expression, and immunohistochemical evidence of liver inflammation, steatosis, and fibrosis." (PMID 38891768, 2024). "However, there are essential questions that need answers: What exactly is the contribution of IL-17 and TLR4 to the development of steatosis and fibrosis in MASLD?" (PMID 39335657, 2024).
steatosis (continued). "In vitro experiments showed that LPS could reduce the activity of steatotic IAR20 cells, aggravate the degree of steatosis, and increase the expression of TLR4." (PMID 35756057, 2022). "However, after treatment with MSCs, the activity of IAR20 cells increased, the degree of cellular steatosis was decreased, and the expression of TLR4 decreased significantly." (PMID 35756057, 2022). "Indeed, the hepatic NPC1L1-mediated steatosis was prevented by the administration of a toll like receptor 4 (TLR4) inhibitor and attenuated by macrophage depletion." (PMID 31883528, 2019). "This trend might imply that hepatic NPC1L1‐dependent re‐uptake of cholesterol followed by the activation of TLR4‐mediated cellular responses may be involved in steatosis formation." (PMID 32123832, 2019). "Furthermore, administration of a TLR4 inhibitor also prevented the hepatic NPC1L1‐mediated steatosis formation, suggesting a latent link between physiological roles of hepatic NPC1L1 and regulation of innate immune system." (PMID 32123832, 2019). "An important question for future studies is to determine whether TLR4 is a dependent or independent factor in the development of hepatic NPC1L1‐mediated steatosis." (PMID 32123832, 2019). "There is strong evidence that TLR stimulation of resident leukocytes occurs during steatosis and Tlr4 is known to induce dendritic cell maturation so it follows that this may be involved in this phenotypic conversion." (PMID 23762326, 2013). "TLR4 signaling is important in both BM-derived cells including Kupffer cells, and endogenous liver cells including hepatic stellate cells (HSCs) for alcohol-induced hepatocyte injury, steatosis, inflammation, and fibrogenesis." (PMID 23087650, 2012). "This event triggers Toll-like receptor 4 (TLR4)-mediated inflammatory cascades in Kupffer cells and hepatocytes, contributing to chronic low-grade inflammation, hepatic insulin resistance, and altered lipid metabolism, thereby promoting progression from steatosis to steatohepatitis and fibrosis." (PMID 40507946, 2025). "Furthermore, increased circulating LPS and increased Toll-like receptor 4 (TLR4) and TGFβ downstream signaling may have an important role in the development of the observed liver microvesicular steatosis and fibrosis." (PMID 36430244, 2022). "Moreover, although the molecular basis remains to be elucidated, simultaneous inhibition of hepatic NPC1L1 and TLR4 might have greater therapeutic effect in treating steatosis versus monotherapy with either inhibitor." (PMID 32123832, 2019). "Indeed, by using this model, we showed that Toll‐like receptor 4 (TLR4) antagonist could potentially serve as a therapeutic agent for steatosis." (PMID 32123832, 2019). "Some preclinical studies have highlighted a marked involvement of TLR4 and TLR9 in the development of steatosis, inflammation, and fibrosis." (PMID 39997751, 2025). "These perturbations activate key pathways, including TLR4/NF-κB-mediated inflammation, FXR-FGF15 axis dysfunction, and oxidative stress, collectively propelling disease progression from steatosis to fibrosis." (PMID 40556760, 2025). "In summary, TLR4 contributes to both the fibrotic and carcinogenic processes in MASLD, playing a central role in the progression from steatosis to cirrhosis and ultimately to HCC." (PMID 39335657, 2024). "HMGB1 exacerbates inflammation through activation of TLR4/MyD88 signaling and RAGE receptors in hepatocytes, resulting in pyroptosis, liver damage, steatosis, and impaired liver function." (PMID 39000266, 2024). "Some preclinical studies have shown a marked involvement of TLR4 and TLR9 in the development of steatosis, inflammation and fibrosis." (PMID 36875849, 2023). "FOS ameliorated hepatic inflammation by reducing the expression of TLR4 and CD14, and improved steatosis and tight junctions by regulating the production of SCFAs." (PMID 35211093, 2022).